OR5B12 (olfactory receptor family 5 subfamily B member 12)
Description:
Odorant receptor.
Synonyms: OR5B12P; OR5B16; OST743; OR11-241
Tractability: Antibody: UniProt places it where antibodies can reach, with medium confidence; UniProt predicts a signal peptide or a membrane-spanning region; its Gene Ontology location is reachable by antibodies, with medium confidence. PROTAC: ubiquitination databases record sites on it.
Gene: Protein-coding gene on chromosome 11 (58,438,994 to 58,442,236, reverse strand). Ensembl gene ENSG00000172362.
Subcellular location: Cell membrane
Pathways (Reactome):
Sensory Perception: Expression and translocation of olfactory receptors
Gene Ontology:
Molecular function: olfactory receptor activity; G protein-coupled receptor activity
Biological process: G protein-coupled receptor signaling pathway; sensory perception of smell; detection of chemical stimulus involved in sensory perception of smell
Cellular component: plasma membrane; membrane
Genetic constraint (gnomAD): Missense variants: 402 observed, 381.69 expected, observed/expected ratio (o/e) 1.05, 90% interval 0.97 to 1.14. Synonymous variants: 152 observed, 140.79 expected, observed/expected ratio (o/e) 1.08, 90% interval 0.94 to 1.24.
Homologues: Orthologues: macaque OR5B12 (92% identical), dog OR5B12 (83% identical), mouse Or5b12 (81% identical), mouse Or5b12b (81% identical), rat Or5b12 (81% identical), rat Or5b12b (80% identical). Paralogues in human: OR5B3 (74% identical), OR5B2 (72% identical), OR5B21 (69% identical), OR5B17 (67% identical), OR8U1 (57% identical), OR5AR1 (56% identical), OR5AP2 (56% identical), OR8U3 (55% identical), OR5AU1 (54% identical), OR9I1 (54% identical), OR8J2 (53% identical), OR8K1 (53% identical), and 84 more.